SULT1D1P (sulfotransferase family 1D member 1, pseudogene)
Synonyms: SULT1D1
Gene: Transcribed unitary pseudogene on chromosome 4 (69,791,872 to 69,813,888, reverse strand). Ensembl gene ENSG00000236959.
Diseases named in the same sentence as SULT1D1P in open-access papers:
SULT1D1P is named in the same sentence as 2 diseases in open-access papers, as found by Europe PMC text mining. Sharing a sentence is not in itself a finding about the gene and the disease.
SULT1D1P shares sentences with these, for which no sentence is quoted: asthma (1 paper); infection (1).